IL1B (interleukin 1 beta)
Diseases named in the same sentence as IL1B in open-access papers (continued):
Sharing a sentence is not in itself a finding about the gene and the disease.
infection (continued). "The present study demonstrated that concentrations of pro-inflammatory cytokines IL-1β, TNF-α, Cox-2 all peaked at 8 weeks post-infection." (PMID 30273397, 2018). "The intracellular localization of TAK1 and TABs was unchanged in AGS cells in response to 40 min of infection with H. pylori or to 10 min of stimulation with TNF or IL-1β." (PMID 29581850, 2018). "Concentrations of inflammatory and immunomodulatory cytokines IL-1β, IL-6, TNF-α, IL-10, and IL-13 were significantly greater in BAL samples of Nrf2 KO mice compared to WT controls at day 1 after infection (p < 0.05)." (PMID 29740449, 2018). "After multiple treatments with insulin, the levels of IL-1β, IL-6, and IFN-γ were increased in the PeLF of diabetic rats after infection with either strain, and CINC-2 levels were restored in N315-infected animals." (PMID 30705678, 2018). "Hence, we speculate that CRP predominantly inhibits trauma-associated release of IL-1β without preventing the IL-1β response to infection." (PMID 30105015, 2018). "As with IL-1β, mRNA levels of the proinflammatory cytokine TNF were significantly upregulated compared to those of the uninfected controls throughout both infection time courses." (PMID 29263113, 2018). "At day 6 post-infection, C57BL/6J mice also exhibited higher levels of IL1A, IL1B, CCL2, CCL3, IL2, IL10, and IL6." (PMID 30713529, 2018). "While for cells with EGDe infection, the alterations of inflammatory cytokines expression were larger with 42.9% TNF‐α reduction and 233.3% IL‐1β increase by 0.5 μmol/L DPI treatment relative to 0 μmol/L DPI treatment." (PMID 30258592, 2018). "Results from our analyses indicated that IL-1β production is significantly enhanced in the skin at the site of GAS infection, and that it is readily detectable by 24 h post-infection, with levels increasing through 72 h post-infection." (PMID 30018884, 2018). "Meanwhile, the expression of NOD2, as well as inflammatory factors IL-1β, TNF-α, and IL-6 was markedly up-regulated in 24 h and 48 h after infection groups." (PMID 30186539, 2018). "RSV infection induces the expression of several pro inflammatory cytokines including IL-1β, IL6 and chemokines such as IL-8 and TNF-α that contribute to inflammation and the pathology of the infection." (PMID 29677209, 2018). "SCRV treatment increased TNFα, IL1β, and IL8 expression at 12 h post-infection in the IRF3 knockdown cells as compared with the control cells." (PMID 29755465, 2018). "The UdLAMPs of both Ureaplasma stimulated the gene expression of IL-1β, TNF-α, TLR2 and TLR4 after 6 and 12 h following infection in macrophages." (PMID 30050519, 2018). "In the context of TC-83 infection, we note that U-87 MG astrocytes produce increased levels of IL-1β, while HMC3 microglia release more IL-1α, IL-1β, IL-6, and IL-8." (PMID 30101649, 2018). "From 8 to 15 days post-infection (dpi), Lena-infection induced higher TNF-α and IL-1β detected in the bronchoalveolar lavage fluid (BALF) and blood compared to those induced by Finistere-infection." (PMID 30469357, 2018). "For samples at 7 dpi, RGV infection alone induced the up-regulation of CD35, GZMB-1, MHC I-3 (Unigene 3 of MHC I) and down-regulation of IL1β." (PMID 29558886, 2018). "And infection of macrophages with the three ΔsurA/SCV1, Δslp/SCV1, and ΔlpoB/SCV1 mutants led to significantly decreased expression of TLR2, TNF-α, IL-1β, and IL-6 compared with those detected in the SCVs." (PMID 29594069, 2018). "In response to inflammation, proinflammatory cytokines (IL-1β and TNF-α) are produced to control infections." (PMID 29849489, 2018). "Oral epithelial cells were shown to express various cytokines and chemokines such as TNF-α, IL-1β, and CCL2 that were upregulated upon infection in our study." (PMID 29967614, 2018). "The most prominently induced genes included IL1B and IL8 (CXCL8), which were upregulated in all isolated cell types after infection of the lung tissue." (PMID 29977236, 2018).
infection (continued). "Our results showed that infection with the PA14 ΔflgK mutant led to reduced IL-18 and IL-1β expression by hCFs." (PMID 28469996, 2017). "The infection stimulated the release of TNF-α, IL-1β, IL-6, IL-8, and IL-10 production by infected cells." (PMID 29118740, 2017). "At all periods after infection analyzed, a decreased number of CD11b+ cells expressing intracellular IL-12, TNF-α, IL-1β, TGF-β, and IL-10 was detected in the lungs of IDO1−/− mice when compared to the WT counterparts." (PMID 28791025, 2017). "This early mucosal resistance phenotype was associated with an early increase of mucosal protein levels of IL-1β, IL-22, KC/CXCL1 and MCP-1 and elevated transcription rates of Cxcl1 and Nos2/iNos measured at 18 hours post infection." (PMID 28662171, 2017). "In M. fortis, the level of IL-1β, GM-CSF, M-CSF, MCP-1, and VEGF increased from the second week post-infection, to concentrations significantly higher than that in C57BL/6 mice." (PMID 28900150, 2017). "Soon after infection (8 hpi), the mRNA levels of the proinflammatory cytokines TNF-α and IL-1β were significantly elevated in the blood of WT and TLR4−/− mice." (PMID 28536433, 2017). "We and others showed previously that IL-1α, IL-1β and IL-18 were increased in the lung of COPD patients and that these mediators were released by epithelial cells on infection with rhinovirus." (PMID 28830544, 2017). "According to data from the literature we considered levels of cytokines IL1β and IL10 and chemokine IL8 to be of greatest interest in STEC-infection." (PMID 28559930, 2017). "In the early stages of infection in our model, it is possible that flagellin and LPS have dual roles in PRR activation and IL-1β production." (PMID 28469996, 2017). "Despite diminished levels of tumour-necrosis factor (TNF), IL-1β, IL-6, IL-12, IL-18 and MCP-1, and decreased neutrophil recruitment to the infection site, resistance to pulmonary tularaemia is increased." (PMID 28580947, 2017). "Whereas the interferons and their receptors appear to be major regulators of viral immune response, lipopolysaccharide, IL1β and TNF are the major regulators of responses activated by infection with M. haemolytica or M. bovis." (PMID 29263411, 2017). "Using J774A.1 mouse macrophages, the effects of Dox on protein and mRNA levels of IL-1β and TNF-α were investigated after infection with live or sonicated Leptospira interrogans serovar Lai strain Lai (56601)." (PMID 28791016, 2017). "Out of the 11 evaluated cytokines only 3, i.e. IL-1β, IL-8 and CXCL9, showed highly increased expression levels in biopsies collected at acute stage of infection when compared to biopsies collected at the convalescent stage." (PMID 28319200, 2017). "The mRNA levels of cytokines in Caco-2 cells measured by qRT-PCR revealed a dramatic increase of IL-1β, IL-8 and TNF-α after infection with S. typhimurium for 2 h." (PMID 29232851, 2017). "The pattern of splicing of genes IL1B, ACSL1 and ATG13 upon infection with H37Ra or H37Rv followed the trend observed in THP-1 macrophages, showing maximum expression in H37Rv infected cells than others." (PMID 28257432, 2017). "While augmentation of TNF signalling by IL1β has been described in macrophages before, we believe that this is the first time that IL1β activation was shown to be enhanced by TNF in Mtb-infection." (PMID 28863187, 2017). "Our findings demonstrated that the genetic deficiency of NLRP3, Casp1/11, and Asc totally impaired the expression of IL-1β, IL-18, NLRP3, Casp1, and ASC mRNA in the lungs of infected mice at week 4 of infection." (PMID 28740491, 2017). "LPS-activated NF-κB in combination with LBP, and triggers the pro-inflammatory mediators of APR, such as IL-1β, IL-6 and TNF-α produced by macrophages or blood monocytes at the site of injury or infection." (PMID 28596485, 2017). "The study established cutoffs facilitating diagnosis on day one of infection: IL-6: 31 pg/mL; TNF-α: 17 pg/mL; IL-1β: 1 pg/mL." (PMID 28487810, 2017).
infection (continued). "SS1/SS1 infection exhibited highest level of TNF-α and IL-1β expression as compared to other groups." (PMID 28286572, 2017). "Ad-SOCS2 infection alleviated STZ-induced renal injury and pathological changes and inhibited STZ-induced IL-6, IL-1β and MCP-1 generation and activation of the TLR4/NF-κB pathway in DN rats." (PMID 29207635, 2017). "The highest levels of gene induction were observed 6 h after infection with wild-type PAO1 and PA14 strains, with significant increases at 3 h observed for il-18 and il-1β only with PA14 (P < 0.05)." (PMID 28469996, 2017). "The analysis of mRNA level of different cytokines revealed a different pattern of induction: IL-1β, IL-6, and IFN-γ are up-regulated in the antrum of mice at early time of infection, while CXCL5 and CXCL15 are induced only at 42 days." (PMID 29085807, 2017). "As early as 12 h post infection, peritoneal CD19(+) cells produce IFN-γ, IL-1β, IL-4, IL-6, IL-12, IL-17, IL-23, and TNF-α." (PMID 29085810, 2017). "These cytokines bind to specific cell surface receptors (IL-1R for IL-1β and TNFR1 or TNFR2 for TNF-α) after release from activated macrophages and/or T cells at the site of infection." (PMID 28270578, 2017). "Based on previous evidences on the immune modulating properties of PE_PGRS33, two pro-inflammatory cytokines, TNF-α and IL-1β, were evaluated by performing a cytometric bead array (CBA) assay on supernatants collected at 72 h from MDMs infection." (PMID 28484686, 2017). "Compared to Mock infection, strain SE2472 infection strongly increased the mRNA levels of inflammatory cytokines including IFN-γ, IL-1β, MIP-2, IL-33, IL-17, IL-22, TNFα, etc.." (PMID 29208934, 2017). "The increased level of IL1β and IL8 during infection is stimulated by both phosphorylated and unphosphorylated CagA, as it triggers the production of NF-κB to almost double." (PMID 28932213, 2017). "Third, influenza A virus (Hkx31; 105 PFU per mouse) infection in mice in vivo for 24 h resulted in greater increases in lung IFN-β, IL-1β, IL-6, and TNF-α mRNA, as well as serum and lung IFN-β protein in NOX2−/y mice." (PMID 28701733, 2017). "Interleukin gene activation was limited to IL1A, IL1B, IL7, and IL15 at 6 h, followed by a downregulated expression of all genes, except IL7, at 16 h of infection." (PMID 28993767, 2017). "Our data indicate that PM1 induces low levels of proinflammatory cytokines IL-6, IL-8 and IL-1β, and the antimicrobial peptide HBD-2, but is able to stimulate, after only 6 h of infection, the expression of the anti-inflammatory cytokine TGF-β." (PMID 28212280, 2017). "Whereas IL-1β and TNF-α are the first cytokines in an infection and are generally pro-inflammatory, IL-6 is secreted thereafter and acts in both pro- and anti-inflammatory roles." (PMID 29078765, 2017). "In a rabbit ear-wound model, mixed species infection of S. aureus and P. aeruginosa caused an increased expression of the pro-inflammatory cytokines IL-1β and TNF-α, indicating a higher inflammatory response compared to single species infection." (PMID 28421166, 2017). "We identified IL-1β as a key cytokine capable of inducing IL-1β, IL-6, TNF-α, and trypsin in mouse lungs and human alveolar A549 cells in the early phase of infection." (PMID 27714503, 2017). "To achieve this, we evaluated the gene expression of pro-inflammatory (IL-1β and IL-6) and one anti-inflammatory cytokine (IL-10), as well as 2 chemokines (IL-8 and RANTES), in NaO-treated bMECs during infection." (PMID 28361042, 2017). "In the sera of M. fortis, the levels of IL-1b, IL-3, IL-4, IL-10, IL-17, MCP-1 and VGF were found to increase from the second to the third week post-infection." (PMID 28900150, 2017). "A reduction in proinflammatory cytokines was observed only after 30 days of infection, considered the resolution stage for murine CBM, and only muriform cells infected animals showed significantly higher levels of IL-1β at this time point." (PMID 28355277, 2017).
infection (continued). "The kinetics of IL-1β mRNA transcription in peritoneal Mφ from WT and TLR2/9−/− mice were analyzed by qPCR at different time points following in vitro infection." (PMID 28222752, 2017). "In our study, the expression levels of IL-1β, IL-10, and IFN-β in the lungs and MHC-II in the brain were upregulated to a remarkably high level after infection with ZH283 and SW8, although were greater for ZH283 than SW8." (PMID 28676793, 2017). "In vivo, after G81007 infection, GLY treatment reduced clinical score and messenger RNA (mRNA) expression of IL-1β, TNF-α, CXCL2 and HMGB1." (PMID 29064403, 2017). "In vivo experiments in chickens further confirmed the observed inflammatory and innate responses induced by vvIBDV in DT40 cells in vitro, and IL-1β, IL-18, TLR1, TLR2, and TLR3 are the predominant DE genes after vvIBDV infection." (PMID 28086922, 2017). "We found that LPS priming of macrophages immediately prior to infection with PE_PGRS41 expressing M. smegmatis, enhances TNF-α, IL-1β and IL-6 mRNA levels and secretion." (PMID 28440335, 2017). "To determine the kinetics of IL-1β secretion, we stimulated THP-1 macrophages with live C. parapsilosis (MOI 5) and examined the production of IL-1β at different intervals post-infection." (PMID 28225025, 2017). "LPS is a potent inductor of pro-inflammatory factors such as TNF-α and IL-1β as well as IL-8 and CXCL family chemokines that reproduce the effect of an infection." (PMID 28486961, 2017). "Infection of these cells induces an early pro-inflammatory immune response by increased expression of cytokines such as IL-12, TNF-α, and IL-1β." (PMID 29379776, 2017). "At 24 h after infection, the expression of cytokines and chemokines (i.e., TNF-α, IL-1β, IL-6, and IL-10) was evaluated by using ELISA." (PMID 28615695, 2017). "It is interesting that despite the induction of proinflammatory cytokines early after infection, CMV suppresses TNF-α and IL-1β signaling pathways at late times, demonstrating unique adaptation capacities that enable virus persistence within the host." (PMID 28241080, 2017). "The gene expression of the pro-inflammatory cytokines IL-1β, IFN-γ and TNF-α along with the anti-inflammatory cytokine IL-10 and selected chemokines were significantly up-regulated throughout infection." (PMID 28814754, 2017). "mRNA levels of IL-1β and TNF-α genes are down-regulated in rainbow trout after infection with Aeromonas salmonicida." (PMID 28542591, 2017). "Flores reported that mice produced significantly less IL-1β and TNF-α during the early phase of infection." (PMID 28785250, 2017). "Interestingly, zebrafish IL-1β can be cleaved into two peptides of 22- and 18-kDa by two distinct caspase 1 homologues after infection with a fish-specific bacterial pathogen Francisella noatunensis, indicating cleavage at multiple sites is possible and may depend on the immunological environment." (PMID 27231948, 2016). "Intracellular WCH-SK2WT infection induced mRNA expression of TLR2, pro-inflammatory cytokines (IL1B, IL6, and IL12) and tissue remodeling factors (MMP9)." (PMID 28083514, 2016). "For the present purpose, we established a rat inflammation model using ip injection of LPS (4 mg/kg, BW) to mimic an infection and found that LPS significantly increased TNF-α and IL-1β levels in the plasma and brain cortex." (PMID 26968975, 2016). "Similar to IL-1β, we observed that MOI 0.1 was a better stimulus to induce MCP-1 and KC expression at early time after infection." (PMID 27833923, 2016). "The secretion of inflammatory cytokines TNF-α, IL-1β, IL-6 and IFN-γ were induced in human PBMC from 1 day after infection." (PMID 27489303, 2016). "We found significantly fewer IL-1β-producing CD11c+CD11b+CD103- and CD11c+CD11b-CD103+ DCs in the lung of Axl-/- mice 72 hr post-infection in comparison to WT mice." (PMID 27350258, 2016).
infection (continued). "In ileum inflammatory genes were overexpressed (e.g., IL-1B, IL-6, IL-8, IL1RAP, TNFα), indicating a strong immune response at all times of infection." (PMID 26738723, 2016). "Cytokines typical of the immune response (IL-1β, IL-2, IFN-γ, IL-4, IL-17A) were analyzed at 2 and 28 days after infection." (PMID 27189736, 2016). "This revealed 13 mediators of inflammation that correlated with infection status, which were, in order of strength of significance, IL-4, IL-5, IL-7, IL-15, IFN-α, IL-12, IFN-γ, IL-17, IL-1Ra, TNF-α, IL-1β, IL-10, and IL-2." (PMID 27418744, 2016). "We found that knockdown of TRIM27 efficiently suppressed the production of IL-1β and IL8 in BCG-infected macrophages since 2 h post-infection, and the complementation with TRIM27 ΔRING exhibited the same suppression effects." (PMID 27698396, 2016). "Levels of cytokine IL-1β and TNF-α in tissue homogenates was determined on different days post infection." (PMID 27333300, 2016). "In the liver, FoxO3a−/− mice had significantly reduced expression of various cytokines such as IL-1β, IL-12, TNF and IFN-γ at day 7 post-infection as measured by qRT-PCR; though the expression of SOCS-1 and SOCS-3 were not altered." (PMID 27599659, 2016). "Three days post infection, sham + IAV + vehicle mice had increased mRNA expression of pro-inflammatory chemokines (CCL-2, CXCL-2, CXCL-10), cytokines (GM-CSF, TNF-α, IL-1β, IL-6) and proteases (MMP-12) compared to sham + diluent + vehicle mice." (PMID 26877172, 2016). "Seven days post infection, CS + IAV mice had increased mRNA expression of pro-inflammatory chemokines (CCL-2, CXCL-2, CXCL-9, CXCL-10), cytokines (GM-CSF, TNF-α, IL-1β, IL-6) and proteases (MMP-12) compared to sham + IAV + diluent mice or CS + diluent mice." (PMID 26877172, 2016). "As expected, following infection with IAV, pulmonary concentrations of IL-1β, TNF-α, IFN-γ, and IL-12p70 were significantly increased during the first week of infection in all females, regardless of P4 treatment (P<0.05)." (PMID 27631986, 2016). "Our systems biology analysis revealed that 13 hub genes, including the classical inflammatory genes (IL6, NFKB2, JUN, IL-1β, and CXCL2) which regulate retinal innate responses during infection." (PMID 26865111, 2016). "Unexpectedly, IL-1β was produced earlier with MOI 0.1 than with MOI 1 and peaked at 18 h after infection and decreased at 24 h after infection." (PMID 27833923, 2016). "On counter with such antigens, the complex interaction of antigen presenting cells, T cells and inflammatory mediators like IL1α, IL1β, TNFα, IL12, IL18 and IL23 lead to proinflammatory immune response and further clearance of infection." (PMID 27301453, 2016). "The transcriptional levels of IL-6, TNF-a, IL-1β and MCP-1 were remarkably increased in the early stage of infection (within 12 h) and gradually decreased to their basal levels by 24 hpi." (PMID 27995095, 2016). "West and colleagues suggested that murine pulmonary infection induced by inhalation of B. pseudomallei leads to increases in IFN-γ, IL-10, IL-1β, IL-6, KC and TNF-α in the lung 1 day after infection." (PMID 27529172, 2016). "Il1b-/- mice showed an even more attenuated phenotype after infection with CFT073, consistent with a key role of IL-1β for bladder inflammation and pathology compared to uninfected bladders." (PMID 27732661, 2016). "Levels of IL-1β and TNF- α, in the sera of mice infected with all MTB strains and treated with G1-4A, started increasing at 15 days post infection, peaked to maximum at 30 days and later declined on 60 days post infection." (PMID 27148868, 2016). "The relative levels of TNF-α, IL-1β, and MMP-9 mRNA transcripts and proteins in the hearts of mice with LCME infection were significantly higher than that in the PBS-injected controls (P < 0.05 for all at all time points)." (PMID 27800490, 2016).